TIMP1 (TIMP metallopeptidase inhibitor 1)
Diseases named in the same sentence as TIMP1 in open-access papers (continued):
Sharing a sentence is not in itself a finding about the gene and the disease.
tumor (continued). "TIMP1 was originally thought to be a tumor suppressor gene, since it could intensely inhibit matrix metalloproteinases (MMPs), canonical oncoproteins." (PMID 33129284, 2020). "Overall, concomitant positive expression of MMP-7 and TIMP-1 might comprehensively evaluate the state of tumour progression and predict the prognosis of patients with GC." (PMID 33005257, 2020). "However, based on the observation of the dynamics of changes depending on the T stage, significantly higher values of TIMP-1 expression were registered in tumor stroma (P=0.0454)." (PMID 31223594, 2019). "Additionally, a correlation study revealed a strong positive correlation between tumour angiogenesis (as demonstrated by VEGF levels) and tumour cell metastasis tendency (as demonstrated by the MMP-2:TIMP-1 ratio) (P < 0.001)." (PMID 31836811, 2019). "Since TIMP molecules, by modulating the activity of metalloproteinases, could affect the behavior of tumor cells as well as endothelial cells, we initially explored the regulation of TIMP-1 by platinum in parental and PT-resistant EOC cells." (PMID 31861382, 2019). "The size of the tumor increased with the decrease of TIMP-1 (T-S)." (PMID 31223594, 2019). "The shorter survival of glioblastoma patients with a high tumor TIMP-1 level may be explained by the antiapoptotic effect of TIMP-1 preventing apoptosis induced by radiation and chemotherapy." (PMID 30867991, 2019). "MMP enzymatic activity is inhibited by the tissue inhibitor of metalloproteinase (TIMP1–4) family of proteins, suggesting that TIMPs may possess anti-tumor activity." (PMID 31882975, 2019). "However, in the analysis of 5-year survival, MMP-2 and MMP-9 both in tumor and stroma, as well as TIMP-1 in stroma, can be useful." (PMID 31223594, 2019). "Surprisingly, we have found TIMP-1 expression in all studied cases of healthy mucous membrane, and the expression level in the matrix and perimatrix of mucosa was significantly higher than that in cancerous tissue and tumor stroma, respectively." (PMID 31143300, 2019). "Third, unlike early stage, advanced EOC seems to take advantage of high TIMP-1 expression, suggesting that in these settings, it could play important functions for tumor progression." (PMID 31861382, 2019). "TIMP-1 serum levels were likewise higher among patients with locally advanced disease (pT4 tumors; P = 0.028), as well as higher among patients with a right-sided tumor (P = 0.016)." (PMID 29929486, 2018). "In addition, it has been proposed that the dysregulation of DNA methylation of RPL30, ALDOB, IGF2, and TIMP1 is sufficient to trigger tumor progression." (PMID 30344796, 2018). "TIMP-1 transcripts are found in both stroma and tumor cells of human PDAC." (PMID 29394913, 2018). "Moreover, recent findings showed that tumor-related myofibroblasts are the major source of elevated TIMP1 expression in GC." (PMID 30065754, 2018). "We then experimentally tested the influence of TIMP1 overexpression on DLD1 tumour growth." (PMID 29367702, 2018). "Indeed, both MMP1 and its inhibitor TIMP1 (tissue inhibitor of metalloproteinases 1) are members of a well-characterized class of proteinases involved in tumor invasiveness and cancer metastases." (PMID 29420626, 2018). "A more recent approach is to increase the TIMP-1 concentration within the tumour tissue." (PMID 29262667, 2017). "Moreover, various studies have correlated Timp1 increased expression in malignant progression and poor prognosis, both in humans and in experimental tumor models." (PMID 28430130, 2017). "To test the hypothesis that TIMP-1 is relevant for fibrosis-driven tumor promotion in the liver we combined DEN-induced hepatocarcinogenesis with fibrogenic liver injury by CCl4." (PMID 28386095, 2017). "Another consideration is that host-derived contributions of TIMP-1 may sufficiently compensate for the effects of RNA interference within the tumor cells." (PMID 29137288, 2017).
tumor (continued). "The biological role of TIMP-1 in reducing tumor invasiveness is well established." (PMID 28108731, 2017). "Moreover, elevated miR-21 expression promoted the tumor cell growth, invasion and migration, and inhibited its apoptosis by targeted PTEN and TIMP1, which was associated with low overall survival." (PMID 28402940, 2017). "As tumor progresses, cells loaded with MMPs accumulate, leading to TIMP-1 and MMP imbalance." (PMID 28030805, 2017). "However, elevated TIMP-1 expression reportedly promoted cancer cell proliferation and invasion and correlated with progression and unfavourable prognosis in certain tumor types." (PMID 28030810, 2017). "Because of its special properties, initially TIMP-1 was considered a tumour suppressing gene." (PMID 29228747, 2017). "Moreover, neutralizing antibodies against TIMP-1 significantly decreased the rate of tumor growth in vivo." (PMID 27130446, 2016). "In addition, TIMP1 was found to decrease tumor cell sensitivity to multiple anticancer drugs by activation of downstream pathways and exhibited anti-apoptotic activity." (PMID 27644693, 2016). "Remarkably, TIMP1 is a secretory protein that could be detected in blood and body fluid, thus making it a good potential tumor marker." (PMID 27644693, 2016). "This will not have a noticeable effect on KRAS wild-type tumor cells, but will reduce the stimulatory drive of extracellular TIMP-1 on KRAS mutated tumor cells." (PMID 27509063, 2016). "In addition to its function as inhibitor of MMPs, TIMP-1 can have tumor-promoting effects, including stimulation of cell proliferation, induction of anti-apoptotic signaling, and support of angiogenesis." (PMID 27509063, 2016). "We investigated whether plasma TIMP-1 protein levels collected prior to surgery correlated with TIMP-1 tumor immunoreactivity." (PMID 27619981, 2016). "Treatment with a neutralizing antibody against TIMP-1 significantly decreased tumor growth in vivo." (PMID 27130446, 2016). "In addition, significant increases were observed for GM-CSF (1.8-fold), Timp-1 (8.6-fold) Serpin E1, and tumor growth inducer HB-EGF (2.3-fold), TSP-1 (2.3-fold), GDNF (1.5-fold) in HT-29 TSs cultured with fibroblasts." (PMID 27391808, 2016). "The effects of inhibiting serpinE2 in tumors are multifaceted: ERK signaling was lowered, CCL2 levels were decreased, a skewing of tumor-promoting M2-like macrophages towards the M1-like phenotype was observed, and the level of the protease inhibitor TIMP1 increased." (PMID 27793045, 2016). "A number of tumor-stimulating functions have been demonstrated for TIMP1." (PMID 26279647, 2015). "It appears that TIMP-1 exerts different effects on tumor progression in various cancers." (PMID 25909286, 2015). "TIMPs including TIMP-1 also play a significant role in tumor development through participation in the degradation of extracellular matrix, in the process of neoangiogenesis and apoptosis, as well as in proliferation of normal and tumor cells." (PMID 26002577, 2015). "Using those mechanisms, TIMP-1 may mutually promote growth, as well as may restrain the proliferation of tumor cells and regulate apoptosis and angiogenesis." (PMID 26002577, 2015). "TIMP-1 is roles in inhibiting tumor cell invasion, as illustrated in multiple studies." (PMID 24978435, 2014). "Among the assessable 264 patients, 210 (80%) had a TIMP-1-positive tumor." (PMID 24884504, 2014). "Mice lacking ASM failed to mobilise tumour inhibitory macrophages in the region of the tumour cells, and lacked tumour-associated hepatofibroblasts, which secrete the matrix metalloprotease inhibitor TIMP1." (PMID 24970218, 2014). "Mechanisms that alter the equilibrium between gelatinase B/MMP-9 and its TIMP-1 inhibitor in favour of protease activity, facilitate gelatinase B/MMP-9 involvement in tumour pathology, and include differential expression, evasion from TIMP inhibition, and TIMP-1 inactivation." (PMID 24473089, 2014).
tumor (continued). "Moreover, TIMP-1 also shares homology with a fibroblast elongation factor that is secreted from colon carcinoma cells and that stimulates tumor cell proliferation." (PMID 23281640, 2013). "A significant correlation was established only between MMP-9/TIMP-1 activities with the tumor size." (PMID 23672427, 2013). "In a mouse model of HCC, TIMP-1 plays an important part in tumor genesis and progression." (PMID 24039823, 2013). "More detailed future studies are required to determine whether the pro-tumor effect of TIMP-1 is MMP-dependent or MMP-independent." (PMID 24143225, 2013). "Similar results have been reported for TIMP-1 levels in tumor tissue extract." (PMID 24330623, 2013). "From the Cox proportional hazards analysis neither the PLA measurements of MMP-9:TIMP-1 (Q2, Q3, or Q4) nor menopausal status, tumor size, lymph node status, or malignancy grade were associated with DFS." (PMID 24330623, 2013). "Also, a non significant difference was reported between the activity of different MMPs with the tumor size except MMP9/TIMP-1, which showed a significant high expression in patients with large tumor size (>5 cm) as compared to low size group (p = 0.032)." (PMID 23672427, 2013). "Successful development of TIMP-1 inhibitors that are capable of blocking its pro-tumor activity requires additional future studies to better understand the molecular bases of the pro-tumor activity of TIMP-1 as TIMP-1 displays both MMP-dependent and MMP-independent functions." (PMID 24143225, 2013). "From the Cox proportional hazards analysis neither the ELISA measurements of MMP-9:TIMP-1 (Q2, Q3, or Q4) nor menopausal status, tumor size, lymph node status, or malignancy grade were associated with DFS." (PMID 24330623, 2013). "The highest TIMP-1 levels were observed in TI, which were 9.1-fold higher than that in L. These data indicate that TIMP-1 is expressed in the tumor as well as in the liver, and that the invasion front compartments exhibit higher TIMP-1 levels than the inner parts of liver and tumor respectively." (PMID 22230683, 2012). "Despite our work suggested that the role of RUNX3 as tumor suppressor might be played through the cell cycle related proteins and TIMP-1, more precise mechanism remained to be elucidated deeply." (PMID 22457727, 2012). "Knowing that TIMP-1 can induce chemoresistance in cancer cells in vitro, one can speculate whether TIMP-1 could be a real target for increasing tumor cell sensitivity to chemotherapy." (PMID 23202950, 2012). "As many chemotherapeutics target cancer cells by inducing apoptosis, this novel observation may be of particular relevance to clinical findings that show a functional relationship between high TIMP-1, resistance to apoptosis, and tumor drug resistance." (PMID 22957045, 2012). "Since we have observed before that over-expression of TIMP-1 in liver host cells leads to efficient tumor growth inhibition in this model, we now examined whether targeting the tumor cells themselves will have a similar effect." (PMID 22230683, 2012). "Paradoxically, for TIMP-1, tumor promoting as well as tumor inhibitory effects have been observed." (PMID 22230683, 2012). "Up-regulation of TIMP-1 was shown to suppress the tumor invasion and metastasis in various human cancers, which may be correlated with its inhibition on MMP-2/9." (PMID 23029478, 2012). "In contrast, TIMP-1 knockdown increased tumor burden dramatically." (PMID 22230683, 2012). "In particular, and consistent with the correlation of TIMP1 expression in CTC and liver metastasis, it has been described as a regulator of the liver microenvironment, increasing the susceptibility of this organ to tumor cells." (PMID 22811761, 2012). "MMP-9 and TIMP-1 have significant potential tumor marker impact in CRC." (PMID 23202950, 2012). "In the survival analysis, elevated tumor TIMP-1 predicted poor patient survival." (PMID 22957045, 2012).
tumor (continued). "Indeed, it has been previously reported that CD82 suppresses tumor invasion by MMP9 inactivation via TIMP1 up-regulation in carcinoma cell line." (PMID 22679510, 2012). "To evaluate any influence of treatment modality, we further examined whether TIMP-1 knockdown in the same animal model would have the opposite effect on tumor growth than TIMP-1 over-expression." (PMID 22230683, 2012). "The urine levels of UTI and serum levels of HA, the SHAP-HA, complex and TIMP-1 were higher in the patients with the poorly differentiated (G3) tumor, compared with the moderately differentiated (G2) tumor and well-differentiated (G1) tumor." (PMID 21904555, 2011). "The control genes (including TIMP1 and the two housekeeping genes) demonstrated comparable expression in tumor and stromal cells for each sample indicating mRNA recovery and quantitation were similar in tumor and stromal cells." (PMID 21170377, 2010). "The interaction analysis which showed a statistically significant association between TIMP-1 and anthracycline therapy in the analyses of OS further suggests that high levels of tumor tissue TIMP-1 are predictive of reduced benefit from adjuvant anthracycline-based therapy." (PMID 19744322, 2009). "We have previously demonstrated that high tumor tissue levels of TIMP-1 are associated with no or limited clinical benefit from chemotherapy with CMF and anthracyclines in metastatic breast cancer patients." (PMID 19744322, 2009). "In these analyses, TIMP-1 was analyzed both as a continuous log-transformed variable and as a dichotomized variable with patients divided into two groups of high and low tumor tissue TIMP-1 levels, respectively, by the median TIMP-1 concentration of the total patient group (12.5 ng/mg protein)." (PMID 19744322, 2009). "Several investigators have reported that TIMP-1 has growth-promoting properties and might also stimulate tumour growth by inhibiting apoptosis." (PMID 15785755, 2005). "Therefore, we investigated the expression of MMP-13 and TIMP1 in biopsy specimens of HNSCCs to determine the relationship between the expression of these proteins and the mode of tumor invasion." (PMID 15291964, 2004). "However, we did fail to identify any statistically significant relationship between the degree of staining for MMP-13 or TIMP-1 and the patient's age, sex, tumor site, or tumor histologic grade." (PMID 15291964, 2004). "We conclude that serum MMP-2 appears to reflect tumour resorption, while serum TIMP-1 may mirror tumour expansion." (PMID 12698191, 2003). "As RT-PCR assay can be performed on biopsy specimens obtained before surgery, an evaluation of the TIMP-1 expression in biopsy specimens by RT-PCR may thus provide useful preoperative information on tumour aggressiveness." (PMID 9275032, 1997). "In addition, TIMP1 has been implicated in ECM remodeling, inflammatory activation, epithelial–mesenchymal transition (EMT), and angiogenesis, collectively contributing to increased tumor cell invasiveness and adaptability." (PMID 41511313, 2025). "Next, we functionally addressed the question, whether a shift to fully glycosylated TIMP-1glyc1/1 can be linked to noncanonic CD63-mediated tumor-promoting effects of TIMP-1, namely tumor cell proliferation and survival." (PMID 40345589, 2025). "However, under hypoxic conditions, the expression dynamics of TIMP1 exhibit a dual nature: it restricts tumor invasion by inhibiting MMP-9 and reducing extracellular matrix degradation, but simultaneously promotes chemoresistance by activating the integrin β1/FAK signaling pathway." (PMID 41189944, 2025). "Moreover, its overexpression is strongly correlated with the immunosuppressive tumor microenvironment, metastatic behavior, and poor patient outcomes, suggesting that TIMP1 could serve as a promising prognostic biomarker for CRC and CRLM." (PMID 41511313, 2025). "Similarly, in cancer, TIMP1 is known to inhibit tumor progression as a natural MMP inhibitor." (PMID 40265926, 2025).
tumor (continued). "Functional enrichment analysis of high TIMP1 expression suggests that TIMP1 may influence tumor invasion and metastasis by regulating ECM remodeling, cell adhesion, cell migration, and related signaling pathways (such as ECM-receptor interaction and cytoskeleton regulation)." (PMID 40313460, 2025). "Importantly, TIMP1 was shown to modulate the tumor immune microenvironment by inducing M2 macrophage polarization via CD63/β1-integrin-mediated activation of the AKT/mTOR signaling pathway, thereby promoting hepatic pre-metastatic niche (PMN) formation and metastatic colonization." (PMID 41511313, 2025). "Additionally, by affecting the expression or activity of TIMP-1, regorafenib might influence the balance between MMPs and TIMPs, potentially enhancing its anti-tumor effects." (PMID 39199626, 2024). "A significantly decreased TIMP1 expression in cancer cells was observed within Nw-PA-T (RQ=0.322, p ≤ 0.001), Ob-PA-T (RQ=0.099, p ≤ 0.001, p2 = 0.01), Nw-MA-T (RQ=0.579, p ≤ 0.001) and Ob-MA-T (RQ=0.121, p ≤ 0.001, p3 ≤ 0.001), which can contribute to tumor migration and progression." (PMID 39072314, 2024). "This suggests that TIMP1 may play a role in tumor invasion, angiogenesis, and metastasis in OC." (PMID 38238592, 2024). "Moreover, in vitro experiments illustrated that inhibition of TIMP1 could inhibit the proliferation, migration, and invasion of LGG cells and also inhibit the polarization of tumor-associated macrophages." (PMID 37264314, 2023). "Furthermore, a protein–protein interaction analysis obtained from the STRING website showed a direct interaction between SPP1 and CD44, MMP3, MMP7, TIMP1 and fibronectin-1, all of which are directly involved in the extracellular matrix remodeling and promotion of tumor metastasis." (PMID 38067407, 2023). "TIMP1 influences key aspects of the TME, such as by activating cancer-associated fibroblasts, leading to extracellular matrix remodeling, regulating inflammation, stimulating epithelial–mesenchymal transition and influencing angiogenesis, thereby promoting tumor aggressiveness." (PMID 37014331, 2023). "Therefore, it is plausible to envisage that tumor cell release of CD63 and TIMP-1 via exosomes might result in the horizontal transfer of malignant traits to recipient cells, thereby promoting tumor progression and resistance to therapy." (PMID 37443843, 2023). "The diagnostic values of anti-POSTN and anti-TIMP1 autoantibodies in ESCC patients of different clinicopathological characteristics, including lymphatic metastasis, distance metastasis, differentiation, TNM stage, family tumor history, gender, and age, were further explored." (PMID 35559040, 2022). "Thus, we aimed to determine whether elevated TIMP1 levels in tumour stroma, relative to those in the tumour cells themselves, are mediated by CRC-EVs." (PMID 35140332, 2022). "In accordance with our hypothesis that the upregulation of TIMP1 level in stromal fibroblasts adjacent to tumour cells is mediated by an EV-mediated crosstalk, we showed that TIMP1 was selectively enriched in CRC-EVs and that TIMP1EV regulated TIMP1 levels in recipient fibroblasts." (PMID 35140332, 2022). "Thus, high-grade tumor budding and expression by MICs of MMP-9, -11, -14, TIMP-1, or TIMP-2 were associated with a poor prognosis in all cases, whereas the association of low tumor budding count and the non-expression of either MMPs or TIMPs was associated with a better outcome." (PMID 33669393, 2021). "However, an altered MMP-9/TIMP-1 ratio is assumed to influence tumor progression." (PMID 33808256, 2021). "In this context, we may also consider that the anti-tumor acivity of AD-MSCs can be to a certain extent clarified by their high amounts of pro-angiogenic molecules and MMPs which secrete, whereas hUCESCs segregate large amounts of TIMP-1 and TIMP-2." (PMID 34112253, 2021).